AREG (amphiregulin)
Diseases named in the same sentence as AREG in open-access papers (continued):
Sharing a sentence is not in itself a finding about the gene and the disease.
COVID-19 (continued). "In COVID-19 patients, AREG is significantly upregulated in PBMCs65, monocytes, CD4 T Cells, NK cells, neutrophils, and DCs61, suggesting that upregulation of AREG may be an attempt to ameliorate the severe injury induced by SARS-CoV-2 infection." (PMID 34262047, 2021). "Additionally, circulating Tregs from patients with severe COVID-19 exhibit decreased amphiregulin expression, suggesting that some of IL-18’s effects may be mitigated by other COVID-19 cytokine storm components." (PMID 36992283, 2023). "In addition, circulating Tregs from severe COVID-19 patients actually show reduced amphiregulin expression, indicating that some aspects of IL-18 effects may be counteracted by other components of the COVID-19 cytokine storm." (PMID 34433692, 2021). "Previous reports have associated differential expression of several constituent genes of the IL2-AIS, including CISH, AREG, DUSP2, NFKBIA and TNFAIP3, in COVID-19 patients." (PMID 37700317, 2023). "Proteins linked to inflammation feature less prominently than in acute COVID-19, whereas upregulation of proteins involved in epithelial damage and repair (e.g., the EGFR ligand AREG and the epithelial marker KRT19) persist." (PMID 35151371, 2022). "Among the upregulated genes in post-COVID-19 monocytes, we still found the acute-COVID-19 upregulated BCL6, AREG and IL-10." (PMID 34572439, 2021). "In this study, we derived three cytokines, IL-6, amphiregulin, and GDF-15, that were related to disease severity in COVID-19 and compared these cytokines between COVID-19 and sepsis." (PMID 35095877, 2021). "Acute COVID-19 monocytes transcriptome showed upregulation of anti-inflammatory tissue repair genes such as BCL6, AREG and IL-10 and increased accessibility of chromatin." (PMID 34572439, 2021). "Data from a single-cell transcriptomic analysis of PBMC in severe COVID-19 patients showed a significant enhancement of MAFF and AREG expression in monocytes." (PMID 34572439, 2021). "Among these proteins, KRT19, TOP2B, AREG, HGF, CKAP4, ITGB6, and NCF2 had a higher expression (> twofold) in plasma samples of severe compared to moderate COVID-19 patients, whereas CLEC4C and LTA were among the few proteins that were expressed at lower levels in severe patients." (PMID 36829233, 2023). "Amphiregulin (AREG), a ligand for epidermal growth factor receptor (EGFR) not known as a major ISG in humans, is barely detectable in healthy control PBMCs but is significantly increased in COVID-19 patients’ monocytes, T cells, NK cells, and DCs." (PMID 35064122, 2022). "Interestingly, although with a lesser intensity, the upregulation of AREG, MAFG, MAFK, BCL6 and IL10 still persisted in monocytes of post-COVID-19 subjects." (PMID 34572439, 2021). "These subsets expressed the amphiregulin (AREG), epiregulin (EREG), and cytokine interleukin-18 (IL-18) genes and appeared to exhibit profibrogenic and proinflammatory features, suggesting that they may be potential targets for COVID-19 treatment." (PMID 36298825, 2022). "Furthermore, a positive correlation was found between the cMono Phenograph clusters specific to severe COVID-19 (clusters 2, 9, 10, and 18) and the soluble immunosuppressive factors IL-10, TGF-β, and VEGFA, as well as with AREG, the latter known to be involved in tolerance and tissue repair." (PMID 33479167, 2021). "In blood, there was upregulation of inflammatory (AREG) and vascular damage (NDRG1) genes in COVID-19 in monocytes but no upregulation of IFNG or IFN-γ response genes." (PMID 39567718, 2024).
asthma (25 papers, 2011 to 2025). "As a member of the epidermal growth factor (EGF)family, amphiregulin (Areg) has been implicated in exerting an important role in regulating tissue repair in acute epithelial injury and asthma." (PMID 36405762, 2022). "AREG expression in structural cells and sputum was associated with asthma severity, and it was shown to be increased in airways during an acute asthma attack." (PMID 33195308, 2020). "Both activin A and amphiregulin have been linked to subepithelial basement membrane thickening in asthma." (PMID 24904541, 2014). "It is, thus, possible that damaged bronchial tissue in cases of severe asthma may be associated with the local accumulation of amphiregulin-producing Treg." (PMID 28066445, 2016). "Furthermore, the specialized proresolving mediator maresin-1 has been shown to reduce asthma-associated bronchial inflammation in a murine model, and this was associated with an increased expression of amphiregulin and de novo generation of CD4+ Tregs." (PMID 28066445, 2016). "In addition, in this study, amphiregulin was also shown to induce proliferation of normal human bronchial epithelial cells, which may be associated with tissue remodeling in asthma." (PMID 28066445, 2016). "Amphiregulin mediates self-renewal in stem cell-like mammary epithelial cells, and has been implicated in epithelial remodeling in asthma, with elevated serum levels immediately following asthma attacks and in mediating proliferation of human bronchial epithelium." (PMID 21572528, 2011). "Our data clearly indicate that mast cells are central to the monitoring of inflammatory niches, and expression of AREG was maintained in asthma biopsies despite treatment." (PMID 40399607, 2025). "The differentially expressed genes included those related to inflammation (CCL22, CXCL16, AREG, MMP12) involved in asthma pathophysiology, as well as genes associated with the skin barrier (IVL, CDSN, SPINK5, FLG)." (PMID 39451560, 2024). "ILC2s release type 2 cytokines (such as IL-5 and IL-13) and growth factors (such as AREG) in inflamed and injured lung tissues in patients with chronic obstructive pulmonary disease and asthma." (PMID 39405112, 2024). "AREG and FN expression colocalized in lung tissues from mice with ovalbumin-induced asthma by immunofluorescence staining." (PMID 36578010, 2022). "Other factors that cause migratory effects in epithelial cells are growth factors TGF-β, EGF and AREG which have been shown to increase in asthma." (PMID 34308764, 2021). "On the other hand, AREG protein level in plasma correlates with the level of periostin, a known marker for Th2 high asthma phenotype, which can predict airway eosinophilia in patients with severe asthma." (PMID 33195308, 2020). "ST2+ memory CD4+ T cells have the capacity to produce high levels of IL-5 and Amphiregulin and are involved in the pathology of asthma." (PMID 30972065, 2019). "A direct action of amphiregulin in recovering the lung function was originally demonstrated in asthma patients and chronic obstructive pulmonary disease patients; influenza virus-infected mice enhanced amphiregulin expression in the lungs and sputum of such patients." (PMID 33670759, 2021). "Interestingly, AREG was upregulated in the acute/exacerbation phase of asthma and returned back to the basal level when the attack subsides." (PMID 33195308, 2020). "In conclusion, our findings suggest circulating AREG expression level can be a reliable, non-invasive, and cost-effective biomarker that can provide additional discriminating power to the available clinical and laboratory tests of asthma." (PMID 33195308, 2020). "However, AREG secretion in conditioned media was higher in bronchial epithelial cells compared to their asthma severity matching bronchial fibroblasts confirming that epithelial cells are the primary source of local lung cells in asthma." (PMID 33195308, 2020).
asthma (continued). "Since, in epithelial cell lines, amphiregulin up-regulates mucine gene expression, while in asthma patients its expression correlates with the extent of goblet cell metaplasia, mast cells could contribute considerably to mucus hypersecretion in asthma." (PMID 28190087, 2017). "Interestingly, amphiregulin is an epidermal growth factor receptor (EGFR) ligand that has been linked to the regulation of tissue repair and remodeling in the context of acute asthma attacks and epithelial injury." (PMID 26965110, 2016). "Importantly, AREG expression was unchanged in asthma samples from epithelial and submucosal niches." (PMID 40399607, 2025). "However, AREG is downregulated in peripheral blood of elderly asthma patients, which may be attributed to the different disease stages." (PMID 34136532, 2021). "In addition, amphiregulin expression in asthma must be interpreted with caution, since elevated levels of amphiregulin have been detected in induced sputum in asthmatic children, where its levels correlated with the numbers of sputum eosinophils and sputum eosinophil cationic protein." (PMID 28066445, 2016). "In this study, we demonstrated that expressions of AREG and FN increased in lung sections from OVA-sensitized mice, which were used as an asthma model." (PMID 36578010, 2022). "Taken together, these results revealed that AREG mediated TGF-β-induced alveolar EMT and contributed to asthma aggravation." (PMID 36578010, 2022). "AREG was found to lead to the proliferation of airway epithelial cells and airway smooth muscle cells through EGFR activation, thereby affecting airway remodeling in severe asthma." (PMID 36578010, 2022). "Previously, high AREG expression was related to lung inflammation, specifically in damaged lung tissues in patients with chronic obstructive pulmonary disease (COPD) and asthma." (PMID 33195308, 2020). "Moreover, AREG is not tumor-specific, but also occurs in the serum of other diseases, such as graft-versus-host disease, idiopathic inflammatory myopathy and asthma." (PMID 36497350, 2022). "Meanwhile, authors have investigated that PM increased the expression of amphiregulin (AREG) in human bronchial epithelial cells (HBECs) and further induced inflammation and mucus hypersecretion via the EGFR-PI3Kα-AKT/ERK pathway, which is known to promote the development and exacerbation of asthma." (PMID 32411804, 2020). "This indicates that AREG can identify a non-eosinophilic subtype of a severe asthma phenotype." (PMID 33195308, 2020).
pancreatic cancer (22 papers, 2010 to 2025). "In a prior study, it was revealed that AREG expression was associated with poor prognosis in pancreatic cancer patients." (PMID 37604948, 2023). "The suppression of AREG has been observed to inhibit the migration and invasion of AsPC-1 cells, a pancreatic cancer cell line." (PMID 39199549, 2024). "In PANC-1 cells, another pancreatic tumor cell line, AREG stimulation increased cell migration, invasion, and the expression of EMT transcription factors." (PMID 39199549, 2024). "Our results support the notion that AREG is overexpressed in pancreatic cancer tissues and cell lines." (PMID 37604948, 2023). "AREG participates in EMT in pancreatic cancer cells through NF-κB signaling and facilitates the movement and spread of pancreatic cancer cells." (PMID 36843929, 2023). "qPCR was used to verify that AREG was knocked down in pancreatic cancer cell lines and that the expression of E-cadherin was upregulated and vimentin was decreased in AREG siRNA-transfected cells." (PMID 37604948, 2023). "Functionally, the deletion of AREG impedes pancreatic cancer (PC) cell proliferation, migration, and invasion." (PMID 37604948, 2023). "In the past, there were a series of attempts to establish AREG as a tumor marker for different tumor entities, such as breast, lung, hepatocellular or pancreatic carcinoma." (PMID 36497350, 2022). "AREG, a ligand of epidermal growth factor receptor (EGFR), is abnormally expressed in multiple types of cancers, such as pancreatic cancer, implicated in mediating the motility, metastasis, and proliferation of tumor cells." (PMID 35237609, 2021). "As VEGF and EGF signalling pathways are inter‐related in pancreatic carcinogenesis, and AREG is an important prognostic factor of pancreatic cancer, we next focused on the possible role of the AREG pathway in the A platensis‐mediated therapeutic effects." (PMID 31957261, 2020). "AREG is upregulated in various neoplasms including colon, lung, liver, breast, prostate, and pancreatic cancer." (PMID 27391842, 2016). "This difference may reflect either the difference between SCC, which is the experimental model in our work, and pancreatic cancer, or that AREG and HB-EGF may trigger different patterns of gene expression." (PMID 39262776, 2024). "However, in this study, the expression of AREG increased in pancreatic cancer cells along with tumor development, as revealed by analyzing sequential single-cell transcriptome analysis of mouse pancreatic cancer development." (PMID 37553567, 2023). "AREG plays a vital function in skin wound healing by stimulating keratinocyte proliferation, and it has been reported that overexpression of AREG induces self-sufficient growth and survival in lung, liver, colon, breast, and pancreatic carcinoma cells." (PMID 35841013, 2022). "However, reports regarding AREG expression in pancreatic cancer by Park showed that decreased expression of AREG was a typical characteristic of the tumor biology." (PMID 27391842, 2016). "Distinct from our work, Mucciolo and colleagues reported that in pancreatic cancer, stromal EGFR activated by AREG is involved in the acquisition of pro-tumorigenic properties that favor cancer cells via myofibroblast activation." (PMID 39262776, 2024). "AREG was demonstrated to induce phosphorylation of ERK1/2 in keratinocytes and pancreatic cancer cells as well as Akt in several cancer cell types." (PMID 32082070, 2019). "To determine if enhancer activity is required for AREG and EREG expression in pancreatic cancer cells, we treated cells with JQ1, a BET bromo-domain inhibitor that is specific for BRD432." (PMID 28733611, 2017). "We modulated GADD45A in pancreatic cancer cells using either siRNA to knockdown or adenoviral infection to overexpress GADD45A and examined the effects on AREG and EREG expression." (PMID 28733611, 2017).
pancreatic cancer (continued). "These genes, AREG, CXCR4, IL11, KITLG and OSCAR, are known to play a significant role in tumour progression and metastasis promotion of prostate cancer as well as colorectal or pancreatic cancers." (PMID 39374163, 2025). "AREG reacts with cancer cells and results in the activation of EGFR in pancreatic cancer." (PMID 34326696, 2021). "Integrin α6β4 is highly expressed in pancreatic carcinoma and contributes to cancer progression, in part, through the specific DNA demethylation and upregulation of epidermal growth factor receptor (EGFR) ligands amphiregulin (AREG) and epiregulin (EREG)." (PMID 28733611, 2017). "Treatment of mice xenografted with human pancreatic cancer with A platensis led to an underexpression of endothelin 1, pentraxin 3 and acidic fibroblast growth factor and an overexpression of 3 angiogenic proteins in tumours, including VEGF‐A and AREG acting via VEGFR or EGFR." (PMID 31957261, 2020).
colitis (18 papers, 2017 to 2025). Inflammation of the colon. "Amphiregulin has been reported to function downstream of the IL-33 pathway to repair epithelial damage caused by dextran sodium sulfate (DSS)-induced colitis." (PMID 38376154, 2024). "Mice with a genetic deficiency of amphiregulin or amphiregulin receptor (EGFR) were found to be susceptible to DSS-induced colitis." (PMID 38376154, 2024). "Parasitic infection during colitis was associated with elevated levels of AREG, EGF, IGFBP-3, and reduced levels of both PDGF-AA and -BB." (PMID 36836678, 2023). "For instance, genes of the EGF-family, such as betacellulin (Btc), previously indicated in ileal growth and homeostasis during health, and amphiregulin (Areg), implicated in intestinal homeostasis during colitis, was induced (Btc) or even de novo expressed (Areg) upon trauma." (PMID 37941007, 2023). "Amphiregulin is known to contribute to intestinal epithelial regeneration, and IL-33 was shown to activate the amphiregulin-EGFR pathway to repair intestinal damage during DSS colitis." (PMID 38376154, 2024). "The exacerbation of colitis induced by neutralization of T1IFN signaling was accompanied by reduction of amphiregulin (AREG) in ILC2s and was partially rescued by exogenous AREG treatment." (PMID 36268010, 2022). "Neutralization of T1IFN signaling exacerbated colitis severity accompanied by a reduction in AREG-producing ILC2s in DSS-induced colitis, which was ameliorated by exogenous treatment with AREG." (PMID 36268010, 2022). "Collectively, these results demonstrate that the T1IFN signaling exacerbation of colitis was partly due to AREG in an ILC2-dependent manner." (PMID 36268010, 2022). "IL-18 has been shown to promote Treg reparative function via amphiregulin, and IL-18 signaling from epithelial cells to Tregs is required for protection against colitis in the RAG transfer model." (PMID 34433692, 2021). "ILC2s repair intestinal epithelial cells in colitis by the production of amphiregulin (AREG), which is the epidermal growth factor-like molecule, following DSS treatment." (PMID 33053762, 2020). "A role of increased expression of amphiregulin by IL-33 has been shown to contribute to control experimental colitis, which merits further investigations." (PMID 31057534, 2019). "IL-33 has also been reported to increase expression of the growth factor amphiregulin to enhance colonic mucin responses in DSS-induced colitis model." (PMID 28710436, 2017). "AREG helps to remodel intestine in inflammatory states such as colitis; however, this may lead to inflammatory bowel disease (IBD) or intestinal fibrosis if not appropriately regulated." (PMID 40725192, 2025). "To investigate the role of T1IFN signaling in ILC2s, we assessed mice treated with anti-T1IFN receptor and observed reduced amphiregulin (AREG) production in ILC2s and exaggeration of colitis in wild-type (WT) and Rag2-deficient mice, which was rescued by supplementation with AREG." (PMID 36268010, 2022). "While evidence on EREG and AREG secretion from CAFs in response to EGFR-targeted therapy is limited, it has been shown that EREG and AREG can be overexpressed and secreted from CAFs in colitis-associated CRC as well as other cancer types to promote tumor progression." (PMID 40727266, 2024). "In our study, we observed a very strong induction of EGF-pathway components during nematode infection, with even higher expressions of AREG and EGF, ligands for EGFR in mice infected with parasites and with induced colitis." (PMID 36836678, 2023). "For instance, in the gut, IL18 signaling promotes Treg function preventing colitis; while in the lung, IL18 signaling induces production of amphiregulin in Tregs, a growth factor promoting tissue repair and homeostasis." (PMID 32687059, 2020).
colitis (continued). "While the precise mechanisms governing ADAM17- and EGFR-mediated protection against DSS-induced colitis remain unknown, the ErbB ligands and known ADAM17 substrates amphiregulin (AREG), epiregulin (EREG), and transforming growth factor (TGF)-α appear to be key effectors." (PMID 29312533, 2017). "A recent study reveals that IL-33 stimulates ILC2 to secrete amphiregulin to promote tissue repair in experimental colitis, suggesting ILC2 at different stage of the disease and/or some subset of ILC2 (i.e., amphiregulin+ ILC2) may have protective function in the resolution of colitis as well." (PMID 29354125, 2017).